CD86 (CD86 molecule)
Diseases named in the same sentence as CD86 in open-access papers (continued):
Sharing a sentence is not in itself a finding about the gene and the disease.
cancer (continued). "In the transwell system, T-DXd failed to induce cGAS-STING pathway activation or upregulation of CD86 and HLA-DR in TDDCs where direct physical interaction between cancer cells and DCs was prevented." (PMID 39449023, 2024). "Precultured with OVA, modified DEXs activated T cells via MHC-antigen peptide complexes and CD86 costimulatory molecules and acted as a bridge between cancer cells and T cells by simultaneously targeting T cell surface CD3 and EGFR on cancer cells." (PMID 38172594, 2024). "Our findings argue that CD86 is a suitable target to inhibit undesired eTreg responses and a potential new candidate to improve Tconv responses to poorly immunogenic cancers, particularly in combination with RT." (PMID 38349740, 2024). "The CD80 (B7-1) and CD86 (B7-2) checkpoint proteins expressed by immune and cancer cells bind to CTLA-4 on T-cells and repress TCR/HLA-class-I-mediated activation." (PMID 37232754, 2023). "On the other hand, Treg cells and regulatory DCs showed ligand–receptor binding through CTLA4-CD80/CD86, which regulate the maturation of tolerogenic DCs, consistent with studies in other cancers." (PMID 37383234, 2023). "Impressively, co-incubation of BMDCs with 4T1 cancer cells pretreated by “M1-MPNPs + L” caused obviously increased expression of CD80 and CD86, suggesting strong DC maturation." (PMID 37626073, 2023). "PEP1 can stimulate DC2.4 cell maturation and up-regulate the expression of the characteristic cell surface molecules MHC-II and CD86, thereby enhancing anti-inflammatory and anti-cancer abilities." (PMID 37446885, 2023). "The pan-cancer analysis showed that CD86 was aberrantly expressed in most cancers compared with that in normal tissues." (PMID 38154107, 2023). "Similar results were obtained for LGASL9 and CD86, remarking a potentially crucial role of these cells in silencing the immune system during cancer progression." (PMID 37460925, 2023). "Studies have found that CD86 is overexpressed in many cancers, especially in AML, and its high expression in AML cell lines has been shown to be associated with poor prognosis." (PMID 37994961, 2023). "Using data from public databases, we found that CD86 is overexpressed in many cancers, and especially in AML." (PMID 37064861, 2023). "ssGSEA method was then used to evaluate the scores of 28 immune cell types in different cancer types, and then calculated the correlation between CD86 and them." (PMID 37064861, 2023). "In subsequent analysis, we gated putative THCs as those co-expressing macrophage CD86 and cancer cell-labeled EGFP markers." (PMID 37848444, 2023). "Flow cytometry analysis showed that cancer cells being engulfed and digested by macrophages displayed CD86+/TiV+/EGFP-." (PMID 37848444, 2023). "The immunological effects of CD86 in various cancers (including on chemokines, immunostimulators, MHC, and receptors) were evaluated through a pan-cancer analysis using TCGA and GEO databases." (PMID 37064861, 2023). "In the cancer setting, comparable levels of antigen loading were observed in the lung and the medLN, but while cDC upregulated CD80 and CD86 in response to both BrightFlu antigen uptake, only CD86 was upregulated in the cancer setting." (PMID 37478193, 2023). "Kaplan–Meier analysis was performed to examine high vs. low CD86 expression in various cancers using TCGA data, and log-rank tests were used for survival analyses." (PMID 37064861, 2023). "The results of univariate Cox regression analysis were then used to create a forest map, which showed that CD86 expression was statistically significant in various cancers." (PMID 37064861, 2023). "PILRΑ expression had a close and positive correlation with three ICGs including LAIR1, HAVCR2 and CD86 in almost all cancer types." (PMID 37652967, 2023). "Meanwhile, we took the orthotopic cancer tissue for IHC analysis, which indicated a decrease in M1 (CD86) and M2 macrophage markers (CD163 and CD206)." (PMID 36612128, 2022).
cancer (continued). "More recently, the abundance and spatial distribution of CD86+ antigen-presenting B cells have been described in tumor samples of cancer patients, indicating that they are elevated in TILs, localized in TLS, and enriched in tumors with increased TLSs." (PMID 35967441, 2022). "Decreased expression of MHC, CD80 and CD86 on APCs correlates with impaired T cell responses and immunosuppression in cancer." (PMID 35660630, 2022). "In most cancers, CD86, TNFSF14, KLRK1, CD48, CD40LG, CD28, C10orf54, ENTPD1, CXCL12, and POLD2 are negatively correlated (p < 0.05)." (PMID 36081989, 2022). "In contrast, VSIR, HAVCR2, and CD86 were negatively correlated with METTL3 expression in several cancer types." (PMID 36614956, 2022). "In this concern, the IL-6 signaling cascade was shown to inhibit the expression of major MHC-II and CD86 molecules on the surfaces of DCs in vivo, resulting in the delay of cancer-related antigen presentation." (PMID 36405719, 2022). "Cancer types where CD86 showed prognostic value in overall survival and disease-specific survival were identified for further analyses." (PMID 33954112, 2021). "The prognostic value of CD86 expression in pan-cancer was analyzed using Cox regression and Kaplan-Meier analysis with data from the cancer genome atlas (TCGA)." (PMID 33954112, 2021). "In the present study, pan-cancer survival analyses revealed prognostic values of CD86 expression in three cancer types, i.e., LGG, SKCM and UVM." (PMID 33954112, 2021). "CTLA-4 upregulation and binding with CD80/CD86 promotes T cell anergy, and cancer cells and TAMs have been shown to express CD80 and CD86." (PMID 34803925, 2021). "The expression levels of CD80 and CD86 in U937 cells co-cultured with rapamycin-pretreated cancer cells were increased compared to those of the control group, whereas, CD163 expression was decreased, in both HeLa and SiHa cell co-cultures." (PMID 33390854, 2021). "RP-182 was found to bind to human and murine CD206+ (M2) TAMs and induce apoptosis and/or repolarization towards a proinflammatory anti-cancer CD86+ M1-like phenotype." (PMID 34988021, 2021). "The intersection of survival analysis with OS and DSS highlighted three cancer types (LGG, SKCM, and UVM), which indicated that CD86 expression has prognostic value in these three cancer types." (PMID 33954112, 2021). "CTLA-4 competes with CD28, a costimulatory receptor, for ligands B7-1 (CD80) and B7-2 (CD86) on cancer cells or antigen-presenting cells." (PMID 32117298, 2020). "The miR-34a-expressed cancer cells more induced THP-1 polarization into M1-like CD86-positive macrophages than that of the scramble cells." (PMID 30885232, 2019). "Phagocytosis of cancer cells by DCs improved after pPBS treatment in all PCC lines and consistent upregulation of the maturation-associated marker CD86 on DCs was observed in cocultures with pPBS-treated MIA-Paca-2 and PANC-1 cells." (PMID 31635070, 2019). "Immunogenicity in vitro was analyzed by co-culturing of dying cancer cells with bone-marrow derived dendritic cells (BMDCs) and rate of phagocytosis and maturation (CD11c+CD86+, CD11c+CD40+) of BMDCs and production of IL-6 in the supernatant were measured." (PMID 31842994, 2019). "The percentage of CD80+CD86+ cells, however, increased by a factor of 2.64 fold in cancer patients upon stimulation, while in healthy subjects this increase was 3.84 fold." (PMID 29975708, 2018). "On the other hand, we observed that within the CD45+ population, the frequency of NK (SSClowCD3−CD16+) cells and M1 macrophages (CD45+CD3−CD11b+CD16+HLA-DR+CD64+CD86+CD206−) was significantly lower in cancer samples than in precursor lesions." (PMID 28827632, 2017). "Considering STAT3 was an important node that mediated cellular responses to cytokines and acted as crucial regulator of PD-L1 and CD86 in cancers, we focused our attention on STAT3." (PMID 29152078, 2017).
cancer (continued). "We also examined the percentage of CD86+/F4/80+ cells in inguinal lymph nodes on day 4 after inoculation with cancer cells." (PMID 24992906, 2014). "For the same activation protocol used in this work we have repeatedly shown a strong upregulation of CD80, CD86 and HLA-DR both for B cells of healthy donors and of cancer patients." (PMID 22592077, 2012). "Notably, abatacept (a CTLA-4-Ig fusion protein that binds CD80/CD86) has demonstrated the ability to modulate T-cell activation and has shown antitumor activity in immunologically active cancers." (PMID 40445003, 2025). "Interestingly, we also show via CD86-labeled, enhancement staining transmission electron microscopy, the internalization and location of hM1-MVs within an OS cancer cell line." (PMID 41148831, 2025). "Therefore, although they express MHC-II molecules, MHC-II+ cancer cells lack CD86 expression (P < 0.001), rendering them incapable of effectively activating CD4+ T cells." (PMID 41281745, 2025). "STAT2 depletion in USP5-deficient cancer cells significantly reduced upregulated CXCL9 and CXCL10 mRNA, as well as CD86 and HLA-DR protein of cocultured THP1-MΦ; these reductions were rescued by restoring WT-STAT2 but not the Y690A mutant in USP5-depleted cells." (PMID 41321309, 2025). "Notably, the immune system-related CD68 and CD86, as well as the cancer-related ERBB2, have a relevance score of 0.8." (PMID 40593564, 2025). "Our analysis of HCC using the TCGA database confirmed the correlation of TKT with additional ICP genes, including CD44, CD80, CD86, and CTLA-4, which may explain the association of TKT overexpression with poorer prognoses in patients with cancer." (PMID 40230848, 2025). "Besides, we also found that only CD276 was positively associated with UBA1 in most cancers, however, there are many other immune checkpoints like CD44, CD86 and CD274 illustrating a positive correlation with UBA6." (PMID 40046044, 2025). "Treg cells have the ability to limit the function of antigen-presenting cells by CTLA-4-dependent downregulation of CD80 and CD86, thereby playing a detrimental role in suppressing cancer progression by evading immune surveillance and suppressing the antitumor immune response." (PMID 38238581, 2024). "In human cancers, antigen-presenting B cells are defined as a subset of CD86+CD21- B cells." (PMID 38384466, 2024). "The results of the association between IFN-γ score and ICG indicated that the IFN-γ scores of virtually all of the different cancers that were investigated had a positive association with the expression of TIGIT, IDO1, ICOS, CD86, CTLA4, HAVCR2, PDCD1LG2, and CD48." (PMID 37646041, 2023). "Furthermore, positive correlations of PRC1 and some immune checkpoint genes (CD274, CTLA4, HAVCR2, LAG3, PDCD1, PDCD1LG2, TIGIT, and CD86) were observed in several cancers, especially BLCA, BRCA, KIRC, LUAD, LIHC, PRAD and THCA." (PMID 37563591, 2023). "On this basis, we hypothesized that the decreased proportion of macrophage CD86 expression (M1-like macrophages) occurred due to the downregulation of IFN-γ in the cancer microenvironment." (PMID 37679802, 2023). "The importance of CD86 as a biomarker in human cancers has been disclosed in previous studies." (PMID 38154107, 2023). "Herein, it was also found that CD86 (M1 macrophages) significantly infiltrated in cancer tissues." (PMID 37306737, 2023). "Using TCGA data on the expression profiles of 33 cancers, CD86 expression was examined." (PMID 37064861, 2023). "This study first explored the expression of CD86 in human cancers." (PMID 38154107, 2023). "Therefore, the interaction of CTLA-4 and CD80/CD86 inhibits the T cell activation signal, resulting in the suspension of the cancer-immunity cycle." (PMID 36980950, 2023). "Furthermore, incubation of D1DCs with PDT-treated cancer cells using the ZnPc-EVs, increased the dendritic cell maturation marker CD86 to levels comparable to incubation with direct TLR-ligand poly I:C." (PMID 35658868, 2022).
cancer (continued). "In addition, B cells from doxorubicin-treated cancer patients were found to have enhanced expression of CD86 with improved APC ability." (PMID 35967441, 2022). "In contrast, when dendritic cells are co-incubated with ferroptotic cancer cells at the intermediate and late stage, they mature to a much greater extent as revealed by increased expression levels of CD86, CD40, and MHCIIhigh, while the expression of PD-L1 decreased." (PMID 35760796, 2022). "Survival Analysis of CD86 expression in pan-cancer was conducted to identify relevant cancer types." (PMID 33954112, 2021). "Due to the fact that CD86 may serve as a key regulator in cancer immune response via T-cell-mediated mechanisms, it has great potential to be a new target of immunotherapy." (PMID 33954112, 2021). "Targeting of CTLA4-CD86/CD86 interaction by the administration of blocking antibodies could enhance the potency of immunotherapy for cancers." (PMID 33868277, 2021). "CD86 has great potential to be a new target of immunotherapy by regulating cancer immune response." (PMID 33954112, 2021). "Also, our data showed that two out of three CMs induced downregulation of the T- cell co-receptor CD86, demonstrating the overall sedentary effect cancer cells have on MΦ." (PMID 34479492, 2021). "Using Kaplan-Meier method, we also conducted pan-cancer survival analysis of CD86 expression." (PMID 33954112, 2021). "The CTLA-4 co-inhibitory receptor is constitutively expressed on T cells and competes with CD28 co-stimulatory receptor for binding to their cognate ligands CD80 (B7.1) and CD86 (B7.2) on cancer cells, for which it has a greater affinity, thereby effectively inhibiting CTL activation." (PMID 33808294, 2021). "The absence or low-level expression of CD80 and CD86 in cancers could be one of the mechanisms in which cancers escape immunosurveillance." (PMID 33092083, 2020). "CD86 also showed a close relation with four cancers, especially in SKCM (cor = 0.860)." (PMID 33344503, 2020). "Moreover, previous studies revealed that CD86 is highly expressed in metastatic gastric carcinoma 24 and the high expression of B7-H3 is commonly found in different cancers and predicts poor patient survival 32-34." (PMID 32025206, 2020). "However, M2 macrophage markers (CD163 and CD206) were advanced and M1 macrophage marker (CD86) was suppressed in THP-1 cells after co-culture with the cancer cells transfected with antago-miR-34a compared with scramble-miR transfectant." (PMID 30885232, 2019). "We also found that CD163 could directly interact with CCL18 and CD86 which were associated with T-lymphocyte activation, indicating CD163 may be involved in cancer immunosurveillance." (PMID 29152078, 2017). "Given that CD86, as a co‐stimulatory molecule, interacts with CD28 for T‐cell activation and survival, the loss of CD86 expression in TAM Macro‐2 may result from a cancer cell‐induced program in the PCa microenvironment." (PMID 38483933, 2024). "However, it remains unclear whether CD86 is a friend or foe in pan-cancer given its dual-edge role in regulating immune response." (PMID 33954112, 2021). "Therefore, CD86+ TAMs are a potentially valuable target for cancer immunotherapy." (PMID 33971970, 2021). "Therefore, in this study, we attempted to convert the negative CTLA4-CD86/CD86 signal by generating a novel CTLA4 signaling pathway in T cells to disrupt the interaction of immune checkpoint inhibitors CTLA4 and CD80/CD86 to effectively treat CD80/CD86-expressing cancer." (PMID 33868277, 2021). "The results showed that the basal expression of the CD80, CD86 and HLA-DR molecules in monocytes, myeloid dendritic cells (mDCs) and plasmacytoid dendritic cells (pDCs) was largely comparable between healthy subjects and cancer patients, before and after the chemotherapy." (PMID 31973714, 2020). "Moreover, lack of meta-analysis on CD86 polymorphisms and cancer risk led us to perform the present study to validate the results." (PMID 25369324, 2014).
cancer (continued). "We found that at baseline the cancer cells in vivo consistently lack CD80 and CD86, but can express PDL1, as anticipated." (PMID 41417245, 2025). "As in the murine models, cancer cells lack costimulation markers, and CD80 and CD86 expression is limited to myeloid populations in the tumors." (PMID 41417245, 2025). "Subsequent analysis of CD86 and CD163 mRNA expression in TAMs cocultured with cancer cells revealed that ANXA2 knockdown increased CD86 expression but suppressed CD163 expression compared with those in the control group." (PMID 39972459, 2025). "CNIH4 was also observed to be significantly positively correlated with multiple immune checkpoints, including CD276, CD86, and PDCD1, in cancers such as KIRC, KIRP, and LGG." (PMID 40051704, 2025). "CD47 is a surface receptor on cancer cell and delivers the “don’t eat me” signal by interacting with SIRPα on myeloid cells, while costimulatory molecules CD80 and CD86 participate in the regulation of antigen presentation and T cell activation." (PMID 40708945, 2025). "Among the validated substrate candidates are the cancer-related ERBB2 as well as the immune system-related CD2, CD68, and CD86." (PMID 40593564, 2025). "In BMDCs, we found upregulation of the costimulatory molecule CD86 upon interaction with necroptotic MOC1 cells which was dependent on active RIPK3 and MLKL in carcinoma cells and was blocked by necrostatin-1." (PMID 40345706, 2025). "Consistently, we confirmed that inhibition MIF in cancer cells and CD74 in microglia promoted M1 polarization, showing upregulated level of CD86 fluorescence intensity and proportion of CD86 + cells." (PMID 38685050, 2024). "Conversely, knockdown of S100A11 in HCC cells increased the expression of anti-cancer M1 macrophage markers CD80 and CD86 but suppressed the expression of pro-cancer M2 markers CD204 and CD206 upon co-culture with THP-1 derived macrophages." (PMID 38169544, 2024). "In contrast, the percentage of CD86-expressing HS cells was consistently lower than in CCH, possibly pointing towards weaker activity of CD86 in the more dedifferentiated and malignant tumor." (PMID 39619201, 2024). "Several inhibitory immunoreceptors, including but not limited to CD28, CD80, CD86, CTLA4, CD276, and CD274, have been identified and studied in cancer in recent decades." (PMID 38831187, 2024). "The obtained results demonstrated significantly elevated levels of CD80, CD86, CD279 and CD274 expressing leukocyte populations in the cancer patient group, while the numbers of NK cells and CD8- and CD25-positive cells were decreased." (PMID 39456247, 2024). "Impressively, the co-incubation of BMDCs with 4T1 cancer cells pretreated with “BC@Z-M + L” markedly increased the expression of maturation markers CD80 and CD86, indicating strong DCs maturation." (PMID 39613774, 2024). "Antigen presenting B cells with a high expression of CD86 and a low expression of CD21 have been shown to localize in TLS in several cancers." (PMID 38361928, 2024). "Oncogenic signaling can also lead to the upregulation of immune-escape proteins in cancers, such as CD274, CD80 and CD86." (PMID 38840185, 2024). "Our data expand on the causes of T-cell suppression as we have further identified an increase in immunosuppressive markers expressed on KEAP1-mutant cancer cells that inhibit the T-cell response (PD-L1, CD80/CD86, and CD155)." (PMID 38542481, 2024). "During the induction phase of the anti-cancer immune response, immune checkpoint molecules inhibit the activation of effector T cells by interfering with the interaction between CD80/CD86 and CD28." (PMID 39507618, 2024). "In response to these cGAS-STING pathway-mediated cytokines, cancer cell fragments/particle-internalized immature DCs differentiate into mature DCs that express CD80 and CD86, as well as robust MHC class II, and exert cross-presentation activity." (PMID 38474078, 2024).